KCNK1 (potassium two pore domain channel subfamily K member 1)
Description:
Ion channel that contributes to passive transmembrane potassium transport and to the regulation of the resting membrane potential in brain astrocytes, but also in kidney and in other tissues. Forms dimeric channels through which potassium ions pass in accordance with their electrochemical gradient. The channel is selective for K(+) ions at physiological potassium concentrations and at neutral pH, but becomes permeable to Na(+) at subphysiological K(+) levels and upon acidification of the extracellular medium. The homodimer has very low potassium channel activity, when expressed in heterologous systems, and can function as weakly inward rectifying potassium channel. Channel activity is modulated by activation of serotonin receptors (By similarity). Heterodimeric channels containing KCNK1 and KCNK2 have much higher activity, and may represent the predominant form in astrocytes (By similarity). Heterodimeric channels containing KCNK1 and KCNK3 or KCNK9 have much higher activity. Heterodimeric channels formed by KCNK1 and KCNK9 may contribute to halothane-sensitive currents. Mediates outward rectifying potassium currents in dentate gyrus granule cells and contributes to the regulation of their resting membrane potential (By similarity). Contributes to the regulation of action potential firing in dentate gyrus granule cells and down-regulates their intrinsic excitability (By similarity). In astrocytes, the heterodimer formed by KCNK1 and KCNK2 is required for rapid glutamate release in response to activation of G protein-coupled receptors, such as F2R and CNR1 (By similarity). Required for normal ion and water transport in the kidney (By similarity). Contributes to the regulation of the resting membrane potential of pancreatic beta cells (By similarity). The low channel activity of homodimeric KCNK1 may be due to sumoylation. The low channel activity may be due to rapid internalization from the cell membrane and retention in recycling endosomes. Permeable to monovalent cations with ion selectivity for K(+) > Rb(+) >> NH4(+) >> Cs(+) = Na(+) = Li(+).
Synonyms: KCNO1; TWIK1; K2p1.1; DPK; TWIK-1; HOHO; K2P1
Tractability: Small molecule: it belongs to a druggable protein family. Antibody: UniProt places it where antibodies can reach, with high confidence; its Gene Ontology location is reachable by antibodies, with high confidence; UniProt predicts a signal peptide or a membrane-spanning region. PROTAC: UniProt records ubiquitination sites on it; ubiquitination databases record sites on it.
Gene: Protein-coding gene on chromosome 1 (233,614,106 to 233,672,514, forward strand). Ensembl gene ENSG00000135750.
Subcellular location: Cell membrane; Recycling endosome; Synaptic cell membrane; Cytoplasmic vesicle; Perikaryon; Cell projection, dendrite; Cell projection; Apical cell membrane
Subcellular location (Human Protein Atlas): Vesicles
Pathways (Reactome):
Muscle contraction: Phase 4 - resting membrane potential
Neuronal System: Tandem of pore domain in a weak inwardly rectifying K+ channels (TWIK)
Gene Ontology:
Molecular function: identical protein binding; potassium channel activity; potassium ion leak channel activity; protein binding; protein heterodimerization activity; sodium channel activity; voltage-gated potassium channel activity; inward rectifier potassium channel activity; ligand-gated channel activity; voltage-gated monoatomic ion channel activity involved in regulation of postsynaptic membrane potential
Biological process: potassium ion transmembrane transport; regulation of resting membrane potential; sodium ion transmembrane transport; chloride transmembrane transport; glutamate secretion; potassium ion transport; cellular response to acidic pH; regulation of postsynaptic membrane potential; response to nicotine
Cellular component: apical plasma membrane; membrane; plasma membrane; potassium channel complex; recycling endosome; cytoplasmic vesicle; perikaryon; synaptic membrane; voltage-gated potassium channel complex; brush border membrane; dendrite; endosome; inward rectifier potassium channel complex
Genetic constraint (gnomAD): Loss-of-function variants: 10 observed, 23.58 expected, observed/expected ratio (o/e) 0.42, 90% interval 0.26 to 0.72. The upper end of that interval is the gene's LOEUF score, 0.72, which puts it in group 2 of 6, group 1 being the genes least tolerant of losing a copy. Missense variants: 378 observed, 430.35 expected, observed/expected ratio (o/e) 0.88, 90% interval 0.81 to 0.96. Synonymous variants: 200 observed, 194.39 expected, observed/expected ratio (o/e) 1.03, 90% interval 0.92 to 1.16.
Homologues: Orthologues: macaque KCNK1 (99% identical), chimpanzee KCNK1 (98% identical), rabbit KCNK1 (97% identical), rat Kcnk1 (96% identical), mouse Kcnk1 (95% identical), guinea pig KCNK1 (95% identical), pig KCNK1 (94% identical), zebrafish kcnk1b (72% identical), zebrafish kcnk1a (70% identical), tropical clawed frog kcnk1 (69% identical), dog KCNK1 (55% identical), Caenorhabditis elegans twk-46 (30% identical), and 12 more. Paralogues in human: KCNK6 (39% identical), KCNK7 (37% identical), KCNK10 (27% identical), KCNK2 (26% identical), KCNK16 (26% identical), KCNK13 (25% identical), KCNK12 (25% identical), KCNK15 (25% identical), KCNK4 (25% identical), KCNK5 (24% identical), KCNK9 (24% identical), KCNK17 (23% identical), and 2 more.
Diseases named in the same sentence as KCNK1 in open-access papers:
KCNK1 is named in the same sentence as 50 diseases in open-access papers, as found by Europe PMC text mining. Sharing a sentence is not in itself a finding about the gene and the disease. The quoted sentences say what the papers report.
breast cancer (14 papers, 2022 to 2025). A primary or metastatic malignant neoplasm involving the breast. "In a similar vein, KCNK1 is overexpressed in breast cancer due to promoter hypomethylation, which is linked to poor prognosis and suboptimal treatment response." (PMID 40469299, 2025). "Surprisingly, further research revealed that KCNK1 expression is considerably upregulated in human breast cancer and is associated with a poor prognosis for breast cancer patients." (PMID 40295451, 2025). "Deregulation via loss of H+-sensitive KCNK1 (among a small group of genes identified) was advantageous for breast cancer cell survival of induced necrosis." (PMID 40867621, 2025). "Potassium Two-Pore Channel Subfamily K Member 1 (KCNK1) is upregulated in various cancers and is associated with a poor prognosis in breast cancer patients." (PMID 39867891, 2024). "In this study, we identified for the first time that the expression of KCNK1 was remarkably up-regulated in breast cancer, which was closely associated with poor prognosis of breast cancer patients." (PMID 38905316, 2024). "Further analysis showed that KCNK1 was positively associated with clinical stage, lymph node metastasis, poor overall survival, and poor relapse-free survival in breast cancer patients." (PMID 38905316, 2024). "KCNK1 encodes a potassium channel with somewhat poorly-defined physiologic roles in both the heart and the brain and has been identified as a potential prognostic biomarker and therapeutic target in breast cancer." (PMID 40013929, 2025). "KCNK1 is a potassium channel differentially expressed in many tumors, but the mechanisms underlying its function in breast cancer remain unclear." (PMID 38905316, 2024). "Similarly, the potassium channel protein KCNK1, which has a two-hole domain (K2P), is dramatically increased in breast cancer tissues and is linked to a poor prognosis." (PMID 36090038, 2022). "In support of finding KCNK genes as DEGs in 20% of the E1–E70 studies, with KCNK1/K2P1 being most frequent, loss of KCNK1 was associated with breast cancer cell survival when necrosis was induced." (PMID 40867621, 2025). "For example, in breast cancer cells, Potassium Two Pore Domain Channel Subfamily K Member 1 (KCNK1) supports the lactylation of H3K18 through LDHA." (PMID 40057816, 2025). "In breast cancer, KCNK1 upregulates LDHA activity and promotes H3K18la enrichment, which in turn increases LDHA gene expression and downstream oncogenes, forming a KCNK1–LDHA–H3K18la–LDHA positive feedback loop that drives metastasis and chemoresistance." (PMID 40843350, 2025). "Further insight into the KCNK1-LDHA pathway should shed light on the design of new targeted drugs for breast cancer treatment." (PMID 38905316, 2024). "To further prove the relationship between KCNK1 and the invasion and migration of breast cancer cells, we conducted a 3D culture experiment." (PMID 38905316, 2024). "The data showed that overexpression of LDHA reduced the adhesion and stiffness of breast cancer cells that were enhanced by KCNK1 knockdown." (PMID 38905316, 2024). "This study shows that KCNK1 is overexpressed in breast cancer promoting proliferation, invasion and metastasis by increasing glycolysis and activating Lactate Dehydrogenase A." (PMID 38905316, 2024). "All these data strongly support that LDHA mediated the functions of KCNK1 on the progression of breast cancer." (PMID 38905316, 2024). "Wound healing and transwell migration assays also showed that LDHA reversed the inhibitory effect of KCNK1 knockdown on the migration ability of breast cancer cells." (PMID 38905316, 2024). "KCNK1 enhances glycolysis and lactate production in breast cancer cells by binding to and activating LDHA, thereby promoting histone Kla." (PMID 39867891, 2024). "Results of MTT and colony formation assays showed that overexpression of KCNK1 promoted the proliferation of breast cancer cells, whereas KCNK1 knockdown inhibited breast cancer cell proliferation." (PMID 38905316, 2024).
breast cancer (continued). "We used GSE65194 to analyze and found that KCNK1 was significantly overexpressed in all breast cancer subtypes compared to normal tissue." (PMID 38905316, 2024). "Transwell invasion assays further confirmed that overexpression of KCNK1 promoted the invasion of breast cancer cells, while knockdown of KCNK1 inhibited its invasion." (PMID 38905316, 2024). "The breast cancer expression profiling datasets GSE42568 and GSE65194 were then analyzed and it was found that 140 genes were up-regulated and positively correlated with KCNK1 expression in breast cancer cells." (PMID 38905316, 2024). "It is of great interest to elucidate the molecular mechanism of KCNK1 in promoting breast cancer proliferation, invasion, and metastasis." (PMID 38905316, 2024). "The results showed that the number of pseudopodia in breast cancer cells was lower after knocking down KCNK1, while the number of pseudopodia in cells increased after overexpressing LDHA." (PMID 38905316, 2024). "Transwell invasion assays also demonstrated that overexpression of LDHA rollbacked the attenuated invasion ability of breast cancer cells induced by the knockdown of KCNK1." (PMID 38905316, 2024). "Meanwhile, we also conducted clamp experiments to detect the effects of overexpression or knockdown of KCNK1 on the resting potential of breast cancer cells." (PMID 38905316, 2024). "In this study, we found for the first time that KCNK1 was significantly up-regulated in human breast cancer and was correlated with poor prognosis in breast cancer patients." (PMID 38905316, 2024). "Wound healing and transwell migration experiments demonstrated that the migration ability of breast cancer cells was enhanced after overexpression of KCNK1 and decreased after KCNK1 knockdown." (PMID 38905316, 2024). "Further studies unexpectedly revealed that KCNK1 contributed to the malignant phenotype of breast cancer by binding to and activating LDHA." (PMID 38905316, 2024). "The results showed that the expression of KCNK1 was indeed elevated in clinical breast cancer samples." (PMID 38905316, 2024). "In contrast, knockdown of KCNK1 enhanced the adhesion and stiffness of breast cancer cells, indicating an attenuated ability to invasion and metastasis." (PMID 38905316, 2024). "Expression of KCNK1/2/3/4/7/9/17 and KCNK1/2/3/7/9/12/13 were the prognostic factor for overall survival and disease-free survival in patients with breast cancer, respectively." (PMID 35656548, 2022). "KCNK1 and KCNK9 were the two most common mutations in breast cancer, occurred in 21% and 18% patients, respectively." (PMID 35656548, 2022). "High expression of KCNK1/3/4/9 was correlated with a poor overall survival in patients with breast cancer." (PMID 35656548, 2022). "We found that KCNK1 and KCNK9 were the two most common mutations in breast cancer, occurring in 21% and 18% of patients, respectively." (PMID 35656548, 2022). "In our study, mRNA expression level of KCNK1 was upregulated in breast cancer tissues with poor overall survival and disease-free survival." (PMID 35656548, 2022). "To investigate whether KCNK1 affects the invasion and migration of breast cancer cells through LDHA, we knocked down KCNK1 in breast cancer cells while overexpressing LDHA." (PMID 38905316, 2024). "This positive feedback mechanism may be responsible for the persistent enhanced lactate production in breast cancer cells with high KCNK1 expression, which consequentially promoted breast carcinogenesis." (PMID 38905316, 2024). "Our data further demonstrated that KCNK1 induced the metabolic reprogramming of breast cancer cells via LDHA, which accelerated lactate production, catalyzed lactylation modifications of a series of downstream target genes, and thus promoted the malignant progression of breast cancer." (PMID 38905316, 2024).
breast cancer (continued). "We detected by AFM that KCNK1 overexpression made cells softer and weakened the adhesion, which might be the reason for the enhanced invasion and metastasis of breast cancer cells." (PMID 38905316, 2024). "In conclusion, our results suggest that KCNK1 may serve as a potential breast cancer biomarker, and deeper insight into the cancer-promoting mechanism of KCNK1 may uncover a novel therapeutic target for breast cancer treatment." (PMID 38905316, 2024). "In addition, MTT and colony formation assays revealed that overexpression of LDHA rescued the inhibitory effect of KCNK1 knockdown on the proliferation of breast cancer cells." (PMID 38905316, 2024). "KCNK1 promoted proliferation, invasion, and metastasis of breast cancer cells in vitro and vivo." (PMID 38905316, 2024). "In addition, results of qRT-PCR and western blotting demonstrated that overexpression of LDHA rescued the expression of downstream targets reduced by knockdown of KCNK1 in breast cancer cells." (PMID 38905316, 2024). "KCNK1 promoted breast cancer proliferation, invasion, and metastasis in vitro and vivo." (PMID 38905316, 2024). "KCNK1 and its downstream genes may serve as new molecular markers for the initial diagnosis and clinical prognosis of breast cancer." (PMID 38905316, 2024). "Potassium Two Pore Domain Channel Subfamily K Member 1 (KCNK1) is differentially expressed in a variety of tumors, but the mechanism of its function in breast cancer is unknown." (PMID 38905316, 2024). "Further studies unexpectedly revealed that KCNK1 increased the glycolysis and lactate production in breast cancer cells by binding to and activating lactate dehydrogenase A (LDHA), which promoted histones lysine lactylation to induce the expression of a series of downstream genes and LDHA itself." (PMID 38905316, 2024). "High expression of KCNK1 and KCNK2 was associated with increasing macrophage in breast cancer." (PMID 35656548, 2022). "In addition, we found that KCNK1/3/7/9/12 was negatively correlated with disease-free survival in patients with breast cancer." (PMID 35656548, 2022). "The authors also proposed that KCNK1 could be a potential biomarker for breast cancer." (PMID 40484921, 2025). "However, further research was necessary to test whether KCNK1 could be a targeted signature in breast cancer therapy." (PMID 35656548, 2022). "According to another investigation, KCNK1 activates LDHA and upregulates H3 K18 lactylation to stimulate the growth and metastasis of breast cancer cells." (PMID 40295451, 2025). "Three ion channel genes KCNK1, CLCN3, and CACNB3, which were overexpressed in breast cancer, and another ion channel gene ANO6, which was underexpressed in breast cancer, were identified by significance analysis of microarrays (SAM)." (PMID 38905316, 2024). "ChIP-qPCR also showed that overexpression of LDHA blocked the inhibitory effect of KCNK1 knockdown on H3K18la and p300 binding of ZWINT, ECT2, ANLN, EZR, and LDHA in breast cancer cells." (PMID 38905316, 2024). "The expression of KCNK1/4/6/9/10/13 were significantly upregulated, while KCNK2/3/5/7/17 were downregulated in breast cancer tissues compared to normal mammary tissues." (PMID 35656548, 2022). "Increased expression of KCNK1/3/4/9 was correlated with poor overall survival, while high expression of KCNK2/7/17 predicted better overall survival in breast cancer." (PMID 35656548, 2022). "KCNK1 is bound to and activates lactate dehydrogenase A (LDHA), which enhances histone lysine lactylation to induce the expression of several downstream genes as well as LDHA itself; this increases glycolysis and lactate generation in breast cancer cells." (PMID 40295451, 2025). "Nevertheless, the proliferation, invasion, and migration of breast cancer were not affected after treatment with KCNK1 inhibitor, indicating that KCNK1 regulated breast tumorigenesis through non-ion channel function." (PMID 38905316, 2024).
breast cancer (continued). "KCNK1 binds to and activates LDHA, promotes lactate production, and catalyzes H3K18la modification of target genes in breast cancer cells, and also raises the level of histone lactylation modification of LDHA itself, which further sustained LDHA expression in a positive feedback loop." (PMID 38905316, 2024). "Among the downstream target genes regulated by KCNK1, ANLN and EZR are involved in cytoskeleton assembly, cell adhesion, and motility, so atomic force microscopy (AFM) was employed to assess the biophysical properties of breast cancer cells." (PMID 38905316, 2024). "KCNK1 expression was positively correlated with that of LDHA, Pan Kla, ZWINT, ECT2, ANLN, and EZR, reconfirming that KCNK1 played an important role in the proliferation and metastasis of breast cancer." (PMID 38905316, 2024). "In this study, we demonstrated that KCNK1 facilitated the malignant process of breast cancer through an unexpected non-ion channel function." (PMID 38905316, 2024). "In conclusion, in this work, we demonstrate for the first time that the potassium channel protein KCNK1 is highly differentially expressed in breast cancer and promotes proliferation, invasion, and metastasis of breast cancer in a non-ion channel-dependent manner." (PMID 38905316, 2024). "The results suggested that KCNK1 might be involved in the malignant process of breast cancer through non-ion channel function." (PMID 38905316, 2024). "These analyses suggest that the expression of KCNK1 is not related to the breast cancer subtypes." (PMID 38905316, 2024). "In addition, KCNK1 is highly expressed in thyroid cancer, breast cancer (BRCA), non-functioning pituitary adenoma, and pancreatic ductal adenocarcinoma, and it can be used as a diagnostic and relevant prognostic marker for tumours." (PMID 38689322, 2024). "However, Quinine, a KCNK1 inhibitor, did not affect the KCNK1-induced color change of the medium, or the proliferation, migration, and invasion of breast cancer cells." (PMID 38905316, 2024).
heart failure (3 papers, 2011 to 2024). Inability of the heart to pump blood at an adequate rate to meet tissue metabolic requirements. "In endomyocardial biopsies from patients with new-onset heart failure, KCNK1 was overexpressed in males." (PMID 39012638, 2024). "In our own studies, AF and heart failure patients showed unchanged cardiac KCNK1 mRNA levels, while others reported upregulation of KCNK1 mRNA patients with atrial dilatation or Brugada syndrome, downregulation of KCNK1 mRNA in AF or mitral valve disease." (PMID 34831137, 2021).